AHR (aryl hydrocarbon receptor)
Diseases named in the same sentence as AHR in open-access papers (continued):
Sharing a sentence is not in itself a finding about the gene and the disease.
breast carcinoma (continued). "Our group reported that resveratrol effectively reversed several epigenetic changes associated with activation of the AhR and its binding to the BRCA1 promoter, in ER/PR positive breast cancer (MCF-7) cells." (PMID 33015128, 2020). "Accordingly, the coexistence of AhR activation and inflammatory conditions are recurring elements in mammary tumors." (PMID 32722276, 2020). "L-dopa was recently reported to suppress cellular growth via down-regulation of prolactin-mediated JAK2/STAT5A in breast cancer cells 50, and carbidopa was reported to be an aryl hydrocarbon receptor agonist and to suppress the growth of pancreatic cancer." (PMID 31598163, 2019). "In this regard, we found that the nuclear shuttle of AHR induced by 3MC in SkBr3 breast cancer cells is prevented either in the presence of the AHR inhibitor CH223191 or using the GPER antagonist G15." (PMID 31370872, 2019). "Breast cancer cells generally express high levels of the AHR, which participate in a large number of endogenous and anti-tumour functions, and studies on human and animals suggest that high AHR expression also concurs with inflammatory conditions." (PMID 30939983, 2019). "For example, the activation of AhR by berberine stimulated the increase of miR-21-3p in a breast cancer cell line." (PMID 31681214, 2019). "In breast cancer, there has been extensive research on the role AhR plays in estrogen-dependent breast cancer." (PMID 31212758, 2019). "As a matter of fact, NCOA7 was previously immunoprecipitated with AhR in human breast cancer cells using AhR-specific antibodies." (PMID 31481962, 2019). "Omeprazole and lansoprazole inhibit polymorphonuclear neutrophil migration and omeprazole decreased migration of a breast cancer cell line that was shown to be dependent on AHR through AHR siRNA experiments." (PMID 31536596, 2019). "Relationship between AHR mRNA expression and classical clinical and pathological parameters in a series of 439 breast cancers." (PMID 29320557, 2018). "AHR mRNA expression level was weakly associated with ERα and HR negative status (p = 0.039 and p = 0.018, respectively) and HR-/ERBB2- breast cancer subtypes (p = 0.047)." (PMID 29320557, 2018). "Cross-talk between AhR and NF-KB pathways has also been implicated in the regulation of AhR-mediated gene transcription such as IL6 and IL8 in breast cancers." (PMID 29320557, 2018). "ER status influences the correlation between AHR expression and the transcription of most of these genes in breast cancers." (PMID 29320557, 2018). "They showed that AhR+ breast cancer patients had a relatively better prognosis than those with AhR− breast cancer because of the effects of activating AhR on cell proliferation and expression of MMPs genes." (PMID 29487603, 2018). "GSEA analysis using the CCLE database demonstrated that AHR expression in 60 breast cancer lines is significantly and positively correlated (false discovery rate = 0.022) with the 10 most altered genes (p = 0.02–0.055) after AHR knockdown." (PMID 29735912, 2018). "Nuclear AhR localization suggests AhR activation in breast cancers due to the presence of exogenous or endogenous ligands." (PMID 29320557, 2018). "Vogel also showed that the high expression of AhR had a positive correlation with NF-κB in breast cancer tissues." (PMID 30275377, 2018). "Growing evidence from animal studies, including those performed on TCDD-exposed rodents during gestation, and on a number of established human breast cancer cell lines, provides substantial support for the role of AhR in mammary tumorigenesis." (PMID 29320557, 2018). "The present study documents the variable expression of AhR in tumors, both in tumor cells and in other cells present in the tumor microenvironment, confirming the complexity of AhR functions in breast cancer." (PMID 29320557, 2018). "Most of these studies were confined to the tumor itself and more attention should be paid to role of the AhR in the microenvironment of breast cancers." (PMID 29487603, 2018).
breast carcinoma (continued). "Saito and colleagues demonstrated the AhR to be a newly defined prognostic factor for breast cancers." (PMID 29487603, 2018). "This has been particularly germane to the potential treatment of breast cancer with AHR “modulators” since both agonists and antagonists have reduced, in different systems, tumor growth." (PMID 29735912, 2018). "Constitutive activation of the AhR has been examined in different models of breast cancer in mice and humans." (PMID 29487603, 2018). "The mechanisms involved in AhR activation and target gene expression in breast cancers are also discussed." (PMID 29320557, 2018). "In this regard, AhR has been shown to inhibit invasive and metastatic potential of human breast cancer stem-like cells." (PMID 29189985, 2018). "Despite clear-cut demonstration of the role of AhR in rodent models of carcinogenesis and in a number of established human breast cancer cell lines, relatively little is known about the roles of AhR in human primary breast tumors." (PMID 29320557, 2018). "ER status is likely to influence the correlation between AHR expression and transcription of most of these genes in breast cancers." (PMID 29320557, 2018). "In contrast to MCF7 cells, in more aggressive MDA-MB-231 breast cancer cells, AhR transcript level showed tendency to augment particularly as a result of treatment with 3MS." (PMID 29189985, 2018). "Several studies have pointed out the inhibition of the ER pathway by AhR in breast cancer as a result of accelerating ER ubiquitination and degradation." (PMID 29189985, 2018). "In this regard, silencing AHR (in the absence of exogenous AHR ligands) in MCF7 and MDA-MB-231 cells decreased the LAT1 mRNA and LAT1 protein, indicating that constitutive AHR activity promotes the transcription of LAT1 in these breast cancer models." (PMID 30103560, 2018). "To address this point, we used human Sum149 breast cancer cells (Sum149 AHRdel cells), in which endogenous AHR expression was deleted using CRISPR/Cas9 technology." (PMID 29563571, 2018). "Following ligand binding in breast cancer cells, AhR can activate two pathways, an X/DRE-mediated DNA binding pathway and/or a non-X/DRE-mediated protein-protein interaction pathway, both of which can lead to changes in gene expression." (PMID 29320557, 2018). "AhR plays a key role in driving normal mammary gland development, and in driving breast cancer progression." (PMID 29320557, 2018). "A major gap in our understanding of AhR activity in mammary tumors is the nature of the signals that drive AhR activation." (PMID 29320557, 2018). "A major gap in our understanding of AhR activity in mammary tumors concerns the nature (exogenous or endogenous) of the signal that constitutively drives AhR activation." (PMID 29320557, 2018). "Rat and mouse primary mammary tumors and human mammary tumor cell lines are characterized by hyperexpression of constitutively active AHR." (PMID 29735912, 2018). "Laboratory research has focused on characterizing aryl hydrocarbon receptor (AhR)-mediated antiestrogenicity in the rodent uterus and mammary and in human breast cancer cells." (PMID 28327540, 2017). "Regulation of microRNAs by the AhR has also recently been demonstrated, with implications for metastasis of breast cancer." (PMID 28424418, 2017). "In breast carcinoma cells, the crosstalk between AhR and ER was recently reported to be transient and immediately disappeared following ligand removal." (PMID 29039776, 2017). "In our previous study, TCDD did induce both aromatase and CYP1A1 via binding to AhR in breast carcinoma cell lines." (PMID 29039776, 2017). "Further, another AHR agonist 2-(4-amino-3-methylphenyl)-5-fluorobenzothiazole also induced DNA damage and cell cycle arrest in breast cancer cells in an AHR-dependent manner." (PMID 27509054, 2016).
breast carcinoma (continued). "Given the pivotal role for Sox2 in stem cell self-renewal, BCSLC development and breast cancer outcomes, AHR/Sox2-specific ChIP assays were performed to determine if the AHR directly interacts with the Sox2 promoter." (PMID 26984638, 2016). "We previously demonstrated that constitutively active AHR in breast cancer lines preferentially drives Cyp1b1 expression while an exogenous ligand, e.g. DMBA, tends to induce greater fold-increases in Cyp1a1 than Cyp1b1." (PMID 26984638, 2016). "Accumulating data suggest that the AHR plays an important role in breast cancer, in general, and in progression to end-stage invasion and migration in particular." (PMID 26984638, 2016). "AHR control of chemoresistance is particularly interesting given important recent studies demonstrating that TCDD decreases and AHR inhibition increases apoptosis induced by UV light or chemotherapeutics in six breast cancer cell lines." (PMID 26984638, 2016). "In a panel of metastatic and invasive human breast cancer cell lines, AhR activation by exogenous ligand blocked their anchorage-independent growth and metastatic potential while promoting their differentiation to a less invasive phenotype." (PMID 27243009, 2016). "Since cancer stem cells contribute to tumor progression, we postulated that the AHR plays a role in the development of breast cancer cells with stem cell-like characteristics (BCSLC)." (PMID 26984638, 2016). "Accumulating evidences suggest Aryl hydrocarbon receptor (Ahr), a helix-loop-helix transcription factor, as a promising target to control migration and invasion in breast cancer cells." (PMID 27907195, 2016). "Stable knockdown of AhR decreased the tumorigenic and metastatic properties of breast cancer cell line in vitro and in vivo." (PMID 26881027, 2016). "Of importance, AhR knockdown downregulated the expression of ABCC3; overexpression of this gene in breast cancer has been strongly associated with acquired MDR and resistance to paclitaxel, a drug widely used in the treatment of metastatic breast cancer." (PMID 26881027, 2016). "We and others have demonstrated that the AHR is highly expressed and constitutively active in breast cancers and that its activity correlates with tumor aggressiveness." (PMID 26984638, 2016). "We have previously published data demonstrating elevated expression of transcriptionally (‘constitutively’) active AHR in human breast cancer cell lines." (PMID 26984638, 2016). "In any case, further experimentation is required to determine how the AHR influences ‘stem-ness’ in breast cancer cells." (PMID 26984638, 2016). "In this study, we demonstrated that AHR directly up-regulates NDRG1 under hypoxia in MCF-7 breast cancer cells." (PMID 26852918, 2016). "The expression of nuclear AHR in ER−/PR−/Her2− human breast cancer-derived Hs578T cells and in inflammatory ER−/PR−/Her2− breast cancer-derived SUM149 cells was consistent with these reports." (PMID 26984638, 2016). "Previously, we reported that AhR agonists repressed estradiol (E2)-dependent BRCA-1 transcription in human breast cancer cells." (PMID 26715507, 2015). "In AhR-activated human breast cancer cells, the pattern of BRCA-1 promoter CpG methylation coincided with the one detected in human sporadic breast tumors." (PMID 26715507, 2015). "Our prior cell culture and rodent model investigations of breast cancer provided evidence that the BRCA-1 gene was a molecular target for the AhR and various chromatin remodeling factors." (PMID 26715507, 2015). "The physical interaction of RelA and AHR is important for the activation of the c-Myc oncogene in breast cancer cells." (PMID 26627005, 2015). "Another member of the NF- κB related factors family is RelA which is found to collaborate with SMAD3, AHR and c-Myc each of which is known to be involved in breast cancer." (PMID 26627005, 2015).
breast carcinoma (continued). "Some studies have described an antiproliferative action of TCDD in ER- breast cancer cell lines through AhR-dependent or AhR-independent pathways." (PMID 25849111, 2015). "Earlier studies documented that the AhR is overexpressed and constitutively activate in rodent and human mammary tumors." (PMID 26715507, 2015). "We evaluated Brca-1 CpG promoter methylation and expression in mammary tumors induced in Sprague–Dawley rats with the AhR agonist and mammary carcinogen 7,12-dimethyl-benzo(a)anthracene (DMBA)." (PMID 26715507, 2015). "Turning to markers of AhR activation, we measured increased Cyp1b1 in adjacent mammary gland and mammary tumors of DMBA-treated animals." (PMID 26715507, 2015). "For this purpose, we adopted the DMBA-rat mammary tumor model based on the knowledge DMBA is a strong AhR agonist and mammary carcinogen." (PMID 26715507, 2015). "The objective of this study was to further investigate potential biomarkers of AF sensitivity, including ERα expression, AhR expression, and AhR signaling in human breast cancer cell lines." (PMID 24885022, 2014). "AhR knockdown downregulated the expression of ABCC3, which is a member of the ABC gene family ABCC3 overexpression is observed in breast cancer and has been implicated in acquired MDR." (PMID 24932473, 2014). "The fact that AhR knockdown alters various genes involved in different biological processes suggests that the role of AhR in breast cancer merits further investigation." (PMID 24932473, 2014). "After screening of the EMT markers, we found that E-cadherin is decreased in kynurenine-treated breast cancer cells, and AhR is involved in this process." (PMID 25060643, 2014). "Interaction between BRCA1 and AhR was enhanced by xenobiotic TCDD in breast cancer cells and BRCA1 was recruited to the promoter regions of CYP1A1 and CYP1B1 along with ARNT/AhR following TCDD exposure." (PMID 24704793, 2014). "We used Affymetrix Human GeneChip 1.0-ST whole transcriptome arrays to analyze alterations of gene expression resulting from stable AhR knockdown in the MDA-MB-231 breast cancer cell line." (PMID 24932473, 2014). "Conversely, AhR depleted clones of the human breast cancer cell line MDA-MB-231 attenuated tumorigenic properties in vitro including proliferation, anchorage independent growth, migration and apoptosis." (PMID 24755659, 2014). "Increasing expression of AhR has been found in breast cancer, gastric cancer, colon adenocarcinoma and lung cancer." (PMID 25226618, 2014). "Aryl hydrocarbon receptor (AhR) has also recently emerged as a potential therapeutic target for breast cancer." (PMID 25403352, 2014). "Subsequently, we showed that knockdown of the inherently elevated levels of AhR in the highly metastatic MDA-MB-231 breast cancer cell line, decreased their tumorigenic properties both in vitro and in vivo." (PMID 24932473, 2014). "Taken together, these findings indicate that YL-109 inhibits breast cancer progression by inducing CHIP expression through AhR signaling." (PMID 25403352, 2014). "In vitro studies have demonstrated that in human breast cancer cells AhR, cyclin D1 and cyclin dependent kinase 4 (CDK4) interact within the cell cycle and the interaction was disrupted upon TCDD treatment." (PMID 24755659, 2014). "Several studies reported higher AhR expression in more malignant breast cancer cell lines as well as a positive correlation with breast tumors aggressiveness." (PMID 25257533, 2014). "The crosstalk between the signaling pathways of AhR and ERα receptors will be the main focus of this review, especially in the context of breast cancer development." (PMID 25257533, 2014). "DIM is an aryl hydrocarbon receptor (AhR) ligand and a potential anticancer agent, namely for the treatment of breast cancer." (PMID 25048790, 2014). "AF was shown to be an agonist of AhR signaling, and AF-induced growth inhibition in renal and breast cancer cells is mediated by AhR activation." (PMID 24885022, 2014).
breast carcinoma (continued). "In particularly, the AhR proved to play a central role in driving the normal mammary gland development, and in an analogous fashion to drive the breast cancer progression." (PMID 25068070, 2013). "Although constitutive expression of SULT1A1 has been associated with cancer cell sensitivity to AF, AhR’s responsiveness to AF, as indicated by induction of CYP1A1, appears to be essential for the antiproliferative activity of AF in breast cancer cell lines." (PMID 24058584, 2013). "In this article we will review the current state of knowledge on the possible role of AhR in breast cancer and how it will be exploited in targeting AhR for breast cancer therapy." (PMID 25068070, 2013). "More relevantly, depletion of AhR in metastatic breast cancer cell line potentiates the efficacy of chemotherapeutic agents and ionizing radiation, increasing the percentage of cells undergoing apoptosis in response to both treatment modalities." (PMID 25068070, 2013). "The AhR is overexpressed and constitutively activated in advanced breast cancer cases and was shown to drive the progression of breast cancer." (PMID 25068070, 2013). "The results of this study provide the impetus for future study investigating the transcriptional mechanisms by which ligand-activated AHR by regulating the expression of prooncogenes modulates mitogenic adipokine signaling in human breast cancer cells." (PMID 24171117, 2013). "Competition binding assays revealed these metabolites as true ligands for AhR but the physiological relevance of their expression and activity in breast cancer needs further investigation." (PMID 25068070, 2013). "Transcriptional pattern analysis revealed that AhR and AhR related genes are frequently deregulated in breast cancer." (PMID 25068070, 2013). "In regards to the role of AhR in breast cancer, large clinical studies as well as further investigations into the molecular mechanism of AhR function are essential." (PMID 25068070, 2013). "But AhR has also been shown to have a role in propelling breast cancer and liver cancer cell differentiation." (PMID 23656719, 2013). "Expression of estrogen receptor α (ERα) and AhR-mediated transcriptional induction of CYP1A1 can sensitize breast cancer cells to AF." (PMID 24058584, 2013). "AhR has been shown to have a role in propelling breast cancer and liver cancer cell differentiation." (PMID 23656719, 2013). "To delineate the role of AhR in the breast cancer progression, we employed the knock-in and knock-down approaches." (PMID 25068070, 2013). "Elevated levels of AhR expression in human mammary tumors were reported from different laboratories including ours." (PMID 25068070, 2013). "Here, we found that tranilast moderately increases the expression of the AHR in MDA-MB-231 breast cancer cells." (PMID 21072210, 2010). "Our results support a role of endogenous AhR in promoting centrosome and centriole amplification in mammary tumors and breast cancer cell lines." (PMID 20565777, 2010). "Most importantly, the AHR is expressed by ER+ and ER− breast cancer cells, and has been found in pre-clinical studies to be an excellent target for the therapy of breast cancer, including triple-negative subtypes (all cell lines examined were AHR+)." (PMID 21072210, 2010). "Results shown here provide compelling evidence that analogues of the bis-indole indirubin, which are known AhR agonists, can suppress centrosome overduplication in breast cancer cell lines in vitro." (PMID 20565777, 2010). "Continued AhR expression was found to be necessary to promote centriole overduplication in HCC1806 breast cancer cells as well as MCF-7 cells stably expression cyclin E to hyperstimulate centriole overduplication." (PMID 20565777, 2010). "We detected nuclear overexpression of the AhR in four of six normal samples (66.7%), 12 of 16 hyperplastic samples (75%), nine of 13 dysplastic samples (69.2%) and 17 of 19 breast cancer samples (89.5%, see Methods for details of scoring procedure)." (PMID 20565777, 2010).